PCNA (proliferating cell nuclear antigen)
Diseases named in the same sentence as PCNA in open-access papers (continued):
Sharing a sentence is not in itself a finding about the gene and the disease.
synovial osteochondromatosis (1 paper, 2024). "Distinguishing primary from secondary synovial osteochondromatosis involves differences in pathological features, proliferating cell nuclear antigen (PCNA) positivity rate in immunological testing, and fibroblast growth factor (FGF9) expression." (PMID 39486129, 2024).
synovitis (1 paper, 2021). Inflammation of a synovial membrane. "In another study, the effect of an ASO aimed at proliferating cell nuclear antigen (PCNA) was studied, which was shown to be effective in suppressing the proliferation of synovitis in a cell model." (PMID 33498456, 2021).
systemic candidiasis (1 paper, 2015). "Hence PCNA may play a critical role in the development of systemic candidiasis and targeting PCNA could develop a new means to combat C. albicans infection." (PMID 26537947, 2015).
systemic sclerosis (1 paper, 2023). A chronic disorder, possibly autoimmune, marked by excessive production of collagen which results in hardening and thickening of body tissues. "In our study, SS-A/Ro60, CENP-B, and Scl-70 in decreasing order were the most common antigens associated with patients of systemic sclerosis, and U1-snRNP, Mi-2, dsDNA, nucleosome, histones, SmD1, PCNA, and SS-A/Ro60 were associated antigens with MCTD in decreasing order." (PMID 38022160, 2023).
Takayasu arteritis (1 paper, 2015). A rare inflammatory large-vessel vasculitis primarily affecting the aorta and its major branches, but also other large vessels, causing stenosis, occlusion, or aneurysm. "Two females presented PCNA antibodies; one was diagnosed with Takayasu arteritis and the other one with SLE plus dilated myocardiopathy." (PMID 26623249, 2015).
thymic lymphoma (1 paper, 2024).
thymoma (1 paper, 2025). A neoplasm arising from the epithelial cells of the thymus. "According to our findings, PCNA expression illustratedatypicalprognostic values in pan-cancer; for example, in adrenocortical carcinoma(ACC), high PCNA levels were linked to poor OS, whereas, in thymoma (THYM), elevatedPCNA expression contributed to better OS." (PMID 40657100, 2025).
thyroid neoplasms (1 paper, 1996).
tongue SCC (1 paper, 2011).
urothelial carcinoma (1 paper, 2020). A malignant neoplasm derived from the transitional epithelium of the urinary tract (urinary bladder, ureter, urethra, or renal pelvis). "Additionally, one neoadjuvantly treated urothelial carcinoma was completely negative (as compared to two untreated cases with moderate IGF1R/PCNA signals)." (PMID 32701997, 2020).
vitamin A deficiency (1 paper, 2020). Deficiency of vitamin A due to malnutrition, malabsorption, or dietary lack. "However, with prolonged vitamin A deficiency, the expression of PCNA was significantly affected." (PMID 32090428, 2020).
Wilms tumor (1 paper, 2017). An embryonal neoplasm characterized by the presence of epithelial, mesenchymal, and blastema components. "These 5 animals presented tumors with histology and cells highly staining positive for PCNA and Wilms' tumor protein antibody characteristics of Wilms' tumor." (PMID 28845162, 2017).
Zinc deficiency (1 paper, 2020). A deficiency of the essential metal Zinc; an essential cofactor for many enzymes. "Alterations of the extracellular matrix, as monitored by increased epidermal growth factor and proliferating cell nuclear antigen (PCNA) immunostaining of rat lungs during zinc deficiency have also been described." (PMID 32754164, 2020).
tumor (1,895 papers, 1992 to 2026). "TISIDB wasused to investigate the association between PCNA gene expression andthe immune microenvironment in pan-cancer, encompassing tumor-infiltratinglymphocytes (TILs), immuno-inhibitors, and chemokines." (PMID 40657100, 2025). "Among these, AOH1996, a first-in-class small-molecule PCNA inhibitor, selectively targets cancer-associated PCNA isoforms, effectively impairing DNA replication and repair in tumor cells while sparing normal cells." (PMID 41170373, 2025). "Within tumor-associated macrophages (TAMs), high PCNA expression has been correlated with poor prognosis, suggesting a role in skewing macrophage function toward a pro-tumorigenic phenotype." (PMID 41170373, 2025). "We checked the tumor size differences in the PCNA amp & 4q loss group, 4q loss group, PCNA amp group, and WT group." (PMID 39762212, 2025). "Previously considered “undruggable” due to its essential role in normal cell survival, tumor–specific post–translational modifications generate a cancer–associated PCNA isoform with unique surface epitopes that can be selectively targeted." (PMID 41190241, 2025). "Although aggressive tumor features are linked to high expression of Ki‐67, PCNA, PHH3, and cyclin D1, their independence as prognostic markers frequently depends on the particular context and patient group." (PMID 40051490, 2025). "A major breakthrough discovery identified a cancer-associated isoform of PCNA (caPCNA), which is highly expressed in tumor tissues but minimally present in normal cells." (PMID 41170373, 2025). "Among these, PCNA-I1 showed selective binding to PCNA trimers, reduced chromatin-associated PCNA, and suppressed tumor growth in various tissue types." (PMID 41170373, 2025). "The C group showed increased PCNA expression, indicating enhanced cell proliferation associated with tumor growth." (PMID 41154100, 2025). "This upregulation often translates to poorer clinical outcomes, as higher PCNA levels have been linked to increased tumor proliferation, enhanced metastatic potential, and reduced patient survival." (PMID 41170373, 2025). "In contrast, anti‐apoptotic Bcl‐2, and proliferation‐associated proteins Ki67 and PCNA, were significantly downregulated, suggesting that the treatment effectively inhibits tumor growth and induces apoptosis." (PMID 40830080, 2025). "Increased expression of Ki67 and PCNA in tumors from food-insecure mice further supports a proliferation-driven mechanism underlying tumor growth in this model." (PMID 40887471, 2025). "IHC performed on the extracted tumor body highlighted that the expression of Ki67 and PCNA was negatively linked to SOX7 expression." (PMID 39227479, 2024). "Based on the findings of our in vivo experiment, we have successfully illustrated that the suppression of RIPK2 effectively impedes the proliferation of tumor cells in vivo through its influence on the cell cycle-associated protein PCNA and apoptosis." (PMID 38164277, 2024). "DNA replication marker PCNA mirrors cell proliferation, while survivin, implicated in tumor growth and spread, plays a key role in these processes." (PMID 38791186, 2024). "In tumor cells, we also found that high baseline expression of specific genes, including PCNA, FGF11, FGF18, CD274 (PD-L1) and HLA-A, was associated with a favorable response." (PMID 38245530, 2024). "PCNA is considered essential for DNA replication in cancer cells and has also been implicated in tumor invasion." (PMID 39346560, 2024). "PCNA was an indicator of cell proliferation and a cofactor for DNA synthase, which was associated with DNA repair and synthesis, PCNA overexpression was often a reliable indicator of tumor progression." (PMID 38689278, 2024). "Firstly, Ki67 and PCNA were selected as markers for cell growth in spheroids tumor, which are associated with the cell cycle, especially during the late G1, S, G2, and M phases, when the cells are rapidly growing and dividing." (PMID 38374894, 2024).
tumor (continued). "TMCC1-AS1 has also been implicated as a tumor promoter; its suppression led to increased E-cadherin expression and decreased proliferating cell nuclear antigen Ki67 expression in HCC cells." (PMID 39434887, 2024). "Next, we performed western blotting assay to measure the expression levels of key protein markers associated with tumor progression, including PCNA, MMP9, and cleaved caspase-3." (PMID 38760791, 2024). "PCNA is also expressed on the surface of certain cancer cells and can play a role in preventing immune cells from killing tumours, as well as being associated with cancer virulence." (PMID 39205238, 2024). "PCNA is reported to be directly linked to the synthesis of cellular DNA, to the grade of tumour differentiation, and to tumour prognosis." (PMID 37242524, 2023). "p21 is a tumor-suppressor gene encoding a protein that competes with DNMT1 for the same binding site on proliferating cell nuclear antigen (PCNA, the homotrimeric ring surrounding DNA) during DNA replication." (PMID 37298139, 2023). "Further, the previous study indicated that the elevated PCNA+ tumor-associated macrophages in early recurrence of BC." (PMID 37531195, 2023). "The study found a rabbit polyclonal antibody (CAPCNAab) that specifically recognizes the tumor-associated PCNA subtype." (PMID 37691919, 2023). "Ki-67 and Proliferating cell nuclear antigen (PCNA) are nuclear proteins associated with cellular proliferation, and Ki-67 is an established surrogate marker of tumor progression." (PMID 37481512, 2023). "Immunohistochemical study revealed that the high expression of Gpx-1 was associated with the tumour’s histological grade, proliferating cell nuclear antigen (PCNA) immunohistochemical expression, depth of invasion, and angioinvasion (all p < 0.001)." (PMID 37242524, 2023). "In CAC, activation of GSDME causes pyroptosis and the release of HMGB1 inducing tumor cell proliferation and proliferating cell nuclear antigen (PCNA) expression through the ERK1/2 pathway and further promoting the development of CAC." (PMID 35411030, 2022). "It has been identify that NKp44 cross-linked Proliferating Cell Nuclear Antigen (PCNA) on tumor cells, and its triggering by agonists led to inhibition of IFNα production in response to CpG." (PMID 36353633, 2022). "Some studies have shown that PCNA is associated with tumor differentiation, penetration, recurrence and lymph node, or organ metastasis." (PMID 36381357, 2022). "One advantage of PCNA as a therapeutic target is based on the cancer-associated PCNA isoform (caPCNA), which appears to be prominently expressed in cancer cells and tumor tissues." (PMID 33498235, 2021). "Data from IHC assay verified similar results that SMO deficiency hindered tumor growth, as the positivity of two proliferative markers (Ki-67 and PCNA) was markedly reduced in tumors with silenced SMO." (PMID 33771969, 2021). "Metformin decreased the expression of cyclin D1 and PCNA which are associated with cell cycle and tumor induction, respectively." (PMID 33893356, 2021). "We examined the proliferation activity of PCNA+ cells, which is associated with tumorigenesis, and found it to be significantly higher in the tumor areas of AOM/DSS mice." (PMID 33808480, 2021). "Cell proliferation markers such as Ki-67 and proliferating-cell nuclear antigen (PCNA) are associated with the inhibition of tumor growth." (PMID 33113766, 2020). "To evaluate the impact of TNFR1 deficiency in tumor cell proliferation we analyzed proliferating cell nuclear antigen (PCNA) in tumor sections." (PMID 33202705, 2020). "NKp30 recognizes B7-H6 tumor antigens, while NKp44 binds proliferating cell nuclear antigen (PCNA) and other tumor-associated ligands." (PMID 33396603, 2020). "Tumor proliferation-associated proteins of PCNA and Cyclin D1 were detected by Western blot assay, whereas cell proliferation was detected by CCK-8 assay." (PMID 33553160, 2020).
tumor (continued). "MCM proteins including MCM7 have been utilized as diagnostic and prognostic tumor markers for their higher specificity and sensitivity than the conventional proliferative markers, such as Ki-67 and PCNA." (PMID 32596300, 2020). "PCNA has also been shown to associate with Human Leukocyte Antigen (HLA) class I molecules on the cell-surface of tumor cells to form an inhibitory ligand for NKp44 and suppression of NK cell cytotoxicity." (PMID 31134055, 2019). "Here, A17pro also significantly suppressed tumor growth, which was again associated with lower numbers of PCNA‐ and pERK1/2‐positive cells in the treated tumor xenografts, as well as reduced levels of serum human sIL‐6R." (PMID 30833304, 2019). "To characterize the features of tumor xenograft model, we performed IHC staining for cell proliferation marker PCNA, microvessel density marker CD34 and metastasis-associated marker MMP-9 in xenograft tissues." (PMID 30791942, 2019). "CBX2 expression level was positively associated with the expression of PCNA and Ki67, two proliferation markers of neoplasm." (PMID 31150156, 2019). "Tumor histology and vascularity were similar between lung tumors from WT and MerTK deficient mice; however, by PCNA immunofluorescence, tumor cell proliferation was significantly reduced in tumors from MerTK deficient mice." (PMID 31903163, 2019). "Peptides mimicking the APIM or a sequence of caPCNA (“cancer associated PCNA”) selectively inhibit tumor cell growth, induce apoptosis, and enhance cytotoxicity of chemotherapy drugs on tumor cells." (PMID 31600334, 2019). "Previously, we identified a novel class of small molecules that bind directly to PCNA, stabilize PCNA trimer structure, reduce chromatin-associated PCNA, selectively inhibit tumor cell growth, and induce apoptosis." (PMID 31600334, 2019). "The prognosis of a GIST is highly associated with mitotic count, tumor size, tumor necrosis, anatomical location, invasive growth, and expression of Ki-67 and PCNA index." (PMID 30515204, 2018). "PCNA and Ki67 are localized in nuclei and are strongly associated with tumor cell proliferation and growth." (PMID 29495605, 2018). "In vitro down-regulation of AB073614 in xenografted mice results in attenuated tumor growth and causes the expression of the proliferation and invasion related proteins PCNA, MMP2 and MMP9 to be decreased." (PMID 28637507, 2017). "G9a depletion suppresses xenograft tumor growth in mouse model, which is linked to a decrease in microvessel density and proliferating cell nuclear antigen expression." (PMID 28977928, 2017). "A second report has also described the interaction of PCNA and NKp44 and the association of PCNA with MHC-I molecules at the plasma membrane of tumor cells as a potential surface transport mechanism." (PMID 28424697, 2017). "Both trophoblasts and tumor cells exhibit high proliferation rates, which are associated with high levels of PCNA." (PMID 27765926, 2016). "KIAA0101 was initially identified by the associate factor of PCNA, which is essential for the proliferation of normal cells and tumor cells." (PMID 27708548, 2016). "The result showed that tumor depth, AJCC stage, LNM stage, distant metastasis, vascular invasion, and expression of LARP1 and PCNA were associated with decreased OS; all these characteristics, except tumor depth, were associated with decreased DFS." (PMID 27614686, 2016). "IHC for PCNA was performed and positive nuclei were counted in the tumor sections of TSP-1-deficient mice and WT mice." (PMID 26461935, 2015). "Previously, we identified nine compounds termed PCNA inhibitors (PCNA-Is) that bind directly to PCNA, stabilize PCNA trimer structure, reduce chromatin-associated PCNA, and selectively inhibit tumor cell growth." (PMID 25729582, 2015). "The association between tumor characteristics (including Gleason score, cancer volume and pathological stage) and EphB6 or PCNA expression were evaluated." (PMID 25789021, 2015).
tumor (continued). "The changes observed in xenografts were associated with decreased PPARβ/δ-dependent expression of proliferating cell nuclear antigen and octamer-binding transcription factor-3/4, suggesting suppressed tumor proliferation and induction of differentiation." (PMID 26431381, 2015). "Compounds structure–activity relationship (SAR)-6 and SAR-24 were analyzed for their effects on and found to reduce chromatin-associated PCNA in tumor cells." (PMID 25729582, 2015). "As tumor associated factors, the expressions of PCNA and NET-1 are closely related to cell proliferation." (PMID 24885292, 2014). "It is known that Dicer can stimulate p-Akt, PCNA and c-Myc expression, which is associated with the enhanced proliferation and invasion in tumor cells." (PMID 24885635, 2014). "We observed a striking difference in tumor growth and subsequent loss of anti-PCNA immunoreactivity." (PMID 24359579, 2013). "Because of its association with cell proliferation, PCNA has been widely used for prognosis of tumor and cancer development." (PMID 23691081, 2013). "Immunohistochemical analysis showed that the positive expression rate of proliferation associated antibody Ki67 and PCNA in tumor was markedly increased." (PMID 24351817, 2013). "Animal experiment showed that the proliferation associated antibodies, Ki67 and PCNA, display high positive expression in tumor tissue, which are decreased by Exendin4 and oxaliplatin." (PMID 24351817, 2013). "In several studies, over-expression (Cyclin D1, NF-κB, PCNA) or loss of expression (Bcl-2) of these markers have been found to correlate with more aggressive tumor growth in CRC." (PMID 23133595, 2012). "High label index of PCNA has been found to be significantly associated with larger tumor size, high recurrence rate and poor survival outcome of HCC patients after hepatectomy." (PMID 22389672, 2012). "Tumor cells with overexpression of Cyclin D1 and c-myc are associated with favorable outcomes while overexpression of p21, p57, and PCNA are linked with adverse outcomes." (PMID 20152033, 2010). "A well or moderate differentiated tumor associated with PCNA positivism below 40% is a good prognosis of the disease." (PMID 20108544, 2009). "The results showed that patients in the PCNA amp & 4q loss group had the largest tumor sizes." (PMID 39762212, 2025). "However, as the data were derived from a heterogeneous cell collection of stromal cells, tumour cells, and surrounding cells, there is no definitive conclusion that the PCNA+ TAMs are M1, but rather that the PCNA+ TAMs are associated with M1-type tumours." (PMID 39205238, 2024). "Moreover, the IHC staining of tumour markers, including Ki67, PCNA, E‐cadherin and N‐cadherin, indicated that the loss of circSTX6 inhibited the proliferation and metastasis of HCC." (PMID 37877357, 2023). "ENSG00000197332, ENSG00000187951, ENSG00000289194, ENSG00000260293, ENSG00000275158, and ENSG00000280206 were inferred as MRs by meta‐PCNA signature, suggesting that these MRs may be more associated with tumor growth than with spread of cancer." (PMID 37644825, 2023). "Similarly to galectin-3, the expression of proliferating cell nuclear antigen (PCNA) that is associated with enhanced tumor cell proliferation and invasive potential, leads to the inhibition of NK cell function via binding to activating NCR receptor NKp44." (PMID 34858978, 2021). "In addition, the positivity of two proliferative markers, Ki‐67 and PCNA, was also lessened in tumours with circ_SMAD4 deficiency." (PMID 33458917, 2021). "There is also a reduction of PCNA expression in association with reduced HCC tumor formation." (PMID 34455417, 2021). "In addition, Ki67 and PCNA, proteins strictly associated with cell proliferation, were found at lower levels in tumor tissues from the sh-C19orf10 groups, compared to that in the control group." (PMID 34093834, 2021).